CD27 (CD27 molecule)
Diseases named in the same sentence as CD27 in open-access papers (continued):
Sharing a sentence is not in itself a finding about the gene and the disease.
infection (continued). "In summary, KSHV-specific CD4+ T cells accumulating at the site of infection remain early differentiated and maintain CD27 expression, while they might acquire a cytotoxic profile in individual subjects." (PMID 41350288, 2025). "In addition, another potentially regulatory T cell subset, CD38+CD27+DN T cells, expanded at week 8–9, after the first infection, as in the previous single-sex 1x CHI13." (PMID 40707512, 2025). "Importantly, the frequency of RBD(WT)+(BA.5.2)+CD19+CD27+ memory B cells was dramatically increased following BA.5.2 infection." (PMID 39257586, 2024). "Furthermore, a population of antigen-specific CD71+CD27+ B cells was previously shown to arise in the blood at the same time of GC formation after infection and vaccination." (PMID 39742271, 2024). "The expression changes in CD21 and CD27 on S+ Bm cells between acute infection and months 6 and 12 post-infection could also be reproduced by manual gating." (PMID 37106039, 2023). "(G) Representative flow plots of CD43 and CD27 expression on P14 cells at day 31 post infection." (PMID 38127070, 2023). "Thus, soluble BTLA and TIM-3 as well as CD27 represent intriguing proteins for further research in burn injury as these proteins may be playing a key role in augmenting an appropriate immune cell response, leaving these individuals highly susceptible to infections." (PMID 35958579, 2022). "However, in children, one year after infection, an increase in the S1-specific IgA class switch and the expression of CD27 on S1-specific B cells and T cell maturation are observed." (PMID 36437276, 2022). "Finally, C2, an IgG-switched conventional (CD21+CD27+) MBC that has been associated with long-lasting B cell memory to SARS-CoV-2 vaccination and infection, was found at v2D28 to correlate with both concurrent (v2D28) and month-6 antibody responses." (PMID 35759653, 2022). "In addition, CD70-expressing immune cells regulate HSPC function and differentiation during infection via CD27 signaling." (PMID 33594067, 2021). "As such, CD27 may be more influenced by infection than disease explaining why it seemed to perform better in young children, where infection is less common among controls." (PMID 34162973, 2021). "Given that there is a relationship between transitional (IgD+, CD38mid) and naïve (IgD+, CD38low, CD27-) it is possible that naïve B cells are acquiring increased CD38 expression as a result of the infection and culture process, and are thus falling into the transitional lineage gate at 3 dpi." (PMID 33075105, 2020). "This leads to enhanced differentiation of naïve T-helper cells into effector T-helper/Memory cells [CD3+CD4+CD8α+CD8β-CD27-], which are capable of secreting high amounts of effector cytokines leading to efficient clearance of heterologous challenge virus at the site of infection." (PMID 33391267, 2020). "Consistent with expectations, the CD27+ γδ T cells were the main producers of IFNγ after infection." (PMID 32636457, 2020). "In addition, it has been described that CD27 plays an important role in the accumulation of antigen-specific CD8+ T cells at the site of infection." (PMID 31694331, 2019). "Interestingly, the frequencies of CXCR5 expressing precursor (CD19+CD27+IgMhiCD21loCD1c+CD10+) and mature MZ-like (CD19+CD27+IgMhiCD21hiCD1c+CD10-) populations remained unaltered during the course of infection in all HIV-1-infected individuals." (PMID 27203285, 2016). "Three days post infection we observed an increased frequency of CD11b+ CD27+ NK cells and a lower frequency of CD11b- CD27+ NK cells in the mLNs, indicating a shift in the NK cell subsets during the early stages of the infection." (PMID 26296209, 2015). "On day 4 after infection, there was a rapid accumulation of CD11b+ CD27+ NK cells and even some CD11b− CD27+ NK cells in the mice primed as neonates, a feature not seen in either naive mice or mice primed as adults, where the majority of NK cells remained the expected CD11b+ CD27− subset." (PMID 24173217, 2014).
infection (continued). "Finally, no significant variations occurred in the resting memory (CD21+CD27+) subset of B cells throughout infection." (PMID 24763747, 2014). "SVV infection induces the proliferation of B cells indicated by an increase in the frequency of Ki67 positive cells on days 7 to 14 compared to day 0 in marginal zone (MZ)-like (CD27+IgD+) and memory (CD27+IgD−) B cells, in BAL cells and PBMC." (PMID 24010815, 2013). "Furthermore, the frequency and signaling profiles of vaccine/pathogen specific B cells (Um cells, as well as Sm CD27+ and Sm CD27− populations) can be assayed in specimens collected from immunized subjects or exposed to natural infection." (PMID 23087912, 2012). "Notably, the frequency of CD27+CD28- cells predominated the HIV-specific CD8+ T cell subset throughout infection, and very few cells transitioned to lose CD27 expression by 23–24 months (mean 3.9%, range 1.1–6.1%)." (PMID 21655252, 2011). "Interestingly, the circulating Active Memory B-cell (Active MB, IgD−/CD21−/CD27+) values measured during the early phase of infection (T0) were significantly higher in the HIV+ patients (median: 43.0%) in comparison with the HIV- patients (median: 18.4%, p = 0.018) or HDs (median: 4.9%)." (PMID 40005722, 2025). "The concomitant downregulation of CD27 on NKG2D-positive γδ T cells as well as the upregulation of CD44 further supports the view that the majority of the γδ T-cell population persists in an effector/memory state even after resolution of the acute phase of the infection." (PMID 25658831, 2015). "Therefore after infection, Lin−Flt3+CD27+IL-7Rα+ CLP cells fall within the LSKint population." (PMID 24825601, 2014). "As increased expression of CD27 in splenic B cells is considered an indication of GC experience, we performed tissue immunofluorescence in splenic sections retrieved from naïve, acutely and chronically-infected monkeys to explore the dynamics of GC development during infection." (PMID 24763747, 2014). "Based on the strict correlation between CD27 expression and myeloid potential in HPCs we could align the infection-induced decrease of functionally-defined myeloid BM progenitors with the reduction in numbers of phenotypically-defined early myeloid progenitors during infection with P. chabaudi." (PMID 23762028, 2013). "Expression of CD27, which is downregulated in some HCMV-specific CD4 T cells during latency, was largely similar to that of naive CD4 T cells at day 8 of infection." (PMID 38236791, 2024). "Here, we revealed a significant decrease in the frequency of memory CD19+ CD27+RBD+ B cells postvaccination and after BA.5.2 infection, potentially resulting in decreased serum antibodies." (PMID 39257586, 2024). "Restimulating mice with S. pneumoniae 6 weeks after primary infection with S. pneumoniae resulted, as expected, an increase in lung CD4+/CD44+/CD62L+ TcM 24 h later, but reduced numbers of CD4+/CD44+/CD62L-/CD27+ effector T cells and their expression of CD103." (PMID 38773113, 2024). "To determine the changes of CD4+ and CD8+ T-cell subset composition among PLWH during breakthrough infection, we used flow cytometry to analyze T-cell subsets according to the expression of CD45RA, CD27, and CCR7." (PMID 38140668, 2023). "In order to characterize in detail the cytotoxic T cell response during incubation as well as early and late acute infection phases, CD8+ cells were analyzed for their activation (CD25, CD38), exhaustion (PD-1) and differentiation status (CD45RA, CD27, CD127)." (PMID 35215797, 2022). "Upon LCMV Armstrong infection, a GP33-specific CD11a+CD43+CD49a+CD27− TRM cell subset was specifically located in the liver, and a Sca-1+CD122+CD27+ TRM cell subset was specific for the lungs." (PMID 33458613, 2021).
infection (continued). "To characterize the state of differentiation of CAR-transduced T lymphocytes in the post-infection period and during antigenic restimulation, we cytometrically analyzed the expression of different surface markers, namely CD62L, CD27, CD28, CCR7, and CD57." (PMID 34660275, 2021). "A TEM cell cluster in the spleen expressing Ly6C, CD27, CXCR3, and CD127 (Sp cluster 12) was more abundant in LCMV Armstrong, whereas a KLRG1+CX3CR1+ subset was more related to MCMV-GP33 infection." (PMID 33458613, 2021). "CD27 is a TNF receptor that stimulates B cells and promotes their differentiation after being activated by the TNF ligand CD70, thereby promoting anti-infection immunity." (PMID 34646272, 2021). "The largest fraction of cells had a central memory phenotype (CD27+, CD45RO+) that remained stable over time, whereas a shift was found to memory precursor cells based on CD127 and KLRG-1 over time after infection." (PMID 34960178, 2021). "Forty-eight hours after infection with LCMV high dose, NK cells exhibited higher expression of activation markers, such as CD11b, CD27, and 4-1BB when compared to low dose infected mice." (PMID 32117809, 2020). "We showed that, in addition to CCR6+ CD27– γδ T cells, the numbers of CCR6–CD27– γδ T cells increased along with their CXCR3 and IL‐17A expression during infection." (PMID 31777067, 2020). "After infection these two MBC sub-classes were reduced and class-switched back to CD27+ classical MBCs." (PMID 31783870, 2019). "CD27 is a member of the TNF receptor family essential for the survival and accumulation of virus-specific T cells at the site of infection." (PMID 29387473, 2018). "According to these findings, it would be interesting to study CD27 and/or CCR4 in samples from active TB patients coming from the site of infection in order to understand better the mechanisms and pathogenesis of the disease." (PMID 30687314, 2018). "In order to assess the activation status in more detail, we analyzed the co-expression of CD27 and CD11b on lung NK cells isolated from uninfected and IAV-infected WT and TLR7ko mice on days 3 and 4 post infection." (PMID 29497422, 2018). "By day 15 post-infection, Zbtb32-/- P14 cells were enriched in memory precursor effector cells (MPEC; IL-7Rhi KLRG-1lo) and a greater proportion expressed CD27, CXCR3 and CD62L compared to WT controls (bottom)." (PMID 28827827, 2017). "Upon pathogen infection, these BAM transform into CD27+CD38+CD138+ PCs that will produce large amounts of antibodies, particularly IgG or IgA." (PMID 29312291, 2017). "At days 9 and 15, we observed a higher proportion and absolute number of Zbtb32-/- compared to WT P14 cells, as well as a greater proportion of Zbtb32-/- P14 cells expressing the memory markers CD27 and CXCR3 at day 9 post-infection (top)." (PMID 28827827, 2017). "cNK cell maturation as measured by CD27, CD11b, and KLRG1 was affected after infection with different parasite strains." (PMID 27721814, 2016). "An inverse, but not statistically significant, relationship between increased CD27+ B cells and Mtb-specific IgG1 suggests that the existing Mtb-specific memory B cells may follow a different pathway of differentiation upon encounter with infection, such as re-entering the GC." (PMID 30271881, 2016). "In contrast, even before infection, a large proportion of RSV-specific CD8+ T cells had already downregulated CD28 and CD27+CD28+ double-positive cells were in the minority." (PMID 26687547, 2015). "Surface marker profiles also differed with time, with expression of CD127, CD62L, CD27, and CD122 increasing and expression of KLRG1 decreasing with time after infection." (PMID 26485703, 2015). "Flagellin427–441-specific T cells started to contract as early as day 10 following infection, and this coincided with a gradual increase in the percentage of cells expressing CCR7 and CD27." (PMID 22275869, 2012).
infection (continued). "The frequency (0.088–3.9% of CD3+CD8+ cells) and phenotype (CD27+CD28−, CD45RA+/−, CD57+/−, HLA-DR+, CD95+) of infant HIV-specific CD8+ T cells were similar to reports in adults undergoing early infection." (PMID 21655252, 2011). "CD27, a T‐cell costimulatory molecule, supports antigen‐specific expansion of naïve T cells, is essential for the primary CD4+ and CD8+ T‐cell responses to infection, and plays a crucial role in the generation of T‐cell memory." (PMID 40746087, 2025). "The general active involvement of the humoral compartment in the MPXV infection was supported by the expansion of the Switched B-cells (SWIBs, CD27+/IgD−/IgM−) from T0 to T2, which were not affected by the HIV coinfection." (PMID 40005722, 2025). "Few months after infection, Scov+ class-switched memory B cells with a resting memory B-cell phenotype (RM, CD19+CD27+CD21+) were predominant compared with those with an activated memory phenotype (AM, CD27+CD21−)." (PMID 40617588, 2025). "It was found that the percentage of CD54 and CD27 expressed on the surface of B cells was significantly higher in the PEDV-QY2016 or PEDV-CV777 strains infection group than those in the negative group." (PMID 38585694, 2024). "At 60 days post‐infection, the spleen of OM‐TB‐TKO mice contained significantly lower frequencies of CD3+ CD4+ T cells, CD69+ CD4+ T cells, CD25+ CD69+ T cells, PD1+ CD27− T cells, and TIM3+ CD4+ T cells, when compared against O‐TB‐TKO or Y‐TB‐TKO mice." (PMID 39039808, 2024). "As expected, the Vax booster enhanced the number of RBD(WT)+CD19+CD27+ memory B cells, while BA.5.2 infection did not further increase cell frequencies." (PMID 39257586, 2024). "Next, we characterized infection of whole-blood-derived B cells by flow cytometry in specific functional B cell subsets (naive CD27− IgD+, memory-switched CD27+ IgD−, memory-unswitched CD27+ IgD+, and double-negative CD27− IgD− cells)." (PMID 35404121, 2022). "Remarkably, soluble CD27 is also significantly increased in burn patients who develop infections relative to those who did not." (PMID 35958579, 2022). "While there is still limited research on soluble CD27, BTLA, and TIM-3, these markers represent highly important indicators (optimal threshold >1129 pg/mL, >1353 pg/mL, and >705.3 pg/mL, respectively) for the development of infection in pediatric burn injury." (PMID 35958579, 2022). "Indeed, after the secondary infection, we observed a significant increase in the percentage of CD19+ CD27+ cells representing the pool of memory B cells and plasmablasts." (PMID 35625758, 2022). "Based on our findings, we hypothesized that the infection of CMV incites extensive memory inflation and a specific differentiation course of CD4+ T cells: first, CD27- effector memory CD4+ T cells that express adhesion molecule CD11a (T-3) are expanded." (PMID 33936035, 2021). "Expansion and maintenance of memory CD8+ T cells are CD4+ T‐cell‐dependent in numerous infection models, with data supporting an essential role of CD4+ T cells in aspects of initial memory CD8+ T‐cell priming through factors such as CD27 and CD40 signalling." (PMID 33005416, 2020). "An increase in the activation threshold, associated with the absence of the costimulatory molecule CD27, increases the affinity for the antigen of the elicited T-cell repertoire and TSLE differentiation after infection." (PMID 33343572, 2020). "Infection of both CP BVDV and NCP BVDV may affect PD-1 expression in CD21+ subpopulations such as CD21+ CD27+ resting memory B cells." (PMID 32256500, 2020). "Accumulation of recent thymic emigrants (RTE), considered as CD4+CD45RA+CD31+ and CD8+CD45RA+CD27+ T-cells, were similar in the three patient groups, and thus identified to be independent of infection history." (PMID 32849561, 2020). "Similarly, others report a T-bet expressing CD27+CD21lo switched memory subset with pre-ASC attributes, which is induced following vaccination or infection." (PMID 31090539, 2019).
infection (continued). "Moreover, using new computational tools, it was recently shown that inflationary MCMV-specific T cells are progressively differentiating in time (based on the markers KLRG1, CD44, CD27 and CD62L), long after the initial infection." (PMID 30989333, 2019). "Overall, our results regarding CD69, CD27, and CD11b expression on lung NK cells show a clear phenotypical activation and maturation in response to IAV infection that increased from days 3 to 4 post infection." (PMID 29497422, 2018). "This study adds novel information on other potential homing biomarkers such as CCR4, showing that in combination with CD27 (CD27−CCR4+IFN-γ+CD4+ T-cells) could be a phenotype to discriminate between disease and infection." (PMID 30687314, 2018). "In humans, we observed that while CD27+ memory B cell numbers did not increase following Bb infection, CD27−IgD− memory B cells exhibited significant increases following Bb infection, peaking at 1 month following completion of doxycycline treatment." (PMID 30072990, 2018). "Targeting this antigen is feasible as CD70/CD27 signaling is not essential for the development of a functional immune system as CD27−/− mice recover from infection in a similar time frame as CD27WT mice." (PMID 30031396, 2018). "While this study included directed sequencing of plasmablasts, as well as total PBMC B cell sequencing, we did not perform directed sequencing of CD27− memory B cells, which we observed to increase following infection." (PMID 30072990, 2018). "Indeed, approximately 50% of HIV-1BAL-infected (p24+) T cells were central memory CD45RO+/CD27+/CD62L+ T cells on day 6 post-infection (p.i.), and 10–20% of infected cells were effector memory (TEM)CD45RO+/ CD27−/CD62L+/− cells." (PMID 30026537, 2018). "In addition, expression of CD127, CD62L, and CD27 progressively increased and expression of KLRG1 progressively decreased with time after infection among CD8lo/CD11ahi cells in individual inbred mice." (PMID 29213267, 2017). "Interestingly, expression of CD127, CD62L, CD27, and KLRG1 among Ag-experienced CD8 T cells was different in individual outbred mice, and these differences were magnified as time passed after infection." (PMID 29213267, 2017). "This indicates that loss of CD27 expression on M. tuberculosis–specific CD4+ T cells, while associated with clinical disease, is not related to time since infection in patients with LTBI." (PMID 28329119, 2017). "CD27 was found decreased in CD56brightCD16dim and CD56dimCD16− but not in CD56dimCD16dim subtypes during infection." (PMID 28674534, 2017). "The percentages of memory B-cells (CD19+CD27+IgD-) did not change after infection with wt EBOV, while disabling of VP35 (but not VP24) IID increased this population." (PMID 27930745, 2016). "Thus PBMC from mice infected with 102 or 106 pfu Smith strain were evaluated 42 weeks after infection for expression of CD44, CD27, CD62L, and KLRG1 on tetramer positive mCMV-specific CD8 T-cells." (PMID 27870919, 2016). "The percentages of cells expressing Ly49H increased significantly in the DN and CD11b-CD27+ subsets of NK cells, but not the more mature DP and CD11b+ CD27− subsets, in rflagellin-treated mice on day 3 after mCMV infection compared with the PBS-treated mice." (PMID 24879439, 2014). "After infection with P. chabaudi the strongly reduced compartment of BM “CD27+ CMPs” and “GMPs” lacked detectable surface levels of CCR2 suggesting that residual myeloid progenitors were unable to egress from the BM via this chemokine-signaling pathway." (PMID 23762028, 2013). "Since HPC including both CD27+ and CD27− subsets did not express message for these genes both in steady state and after infection (data not shown) the increase in chemokine message was most likely due to their induction in stromal and vascular cells." (PMID 23762028, 2013).